SPARC (secreted protein acidic and cysteine rich)
Diseases named in the same sentence as SPARC in open-access papers (continued):
Sharing a sentence is not in itself a finding about the gene and the disease.
pancreatic cancer (80 papers, 2007 to 2025). "A similar stromal enrichment of SPARC has been documented in pancreatic cancer, where it is associated with poor prognosis." (PMID 41018070, 2025). "In pancreatic cancer, the expression of SPARC by peritumoral fibroblasts is associated with a poorer prognosis for patients." (PMID 37046676, 2023). "While murine mammary cancer cells transplanted in SPARC-deficient mice formed smaller tumors compared with controls, murine pancreatic cancer cells, Lewis lung cancer cells and lymphoma cells formed larger tumors and increased metastasis in the mice." (PMID 33579227, 2021). "Expression of the SPARC gene, which encodes a protein involved in the remodeling of the extracellular matrix in pancreatic cancer, is characteristic of both cancer cells and CAFs, but in the latter, its expression is much higher." (PMID 33804861, 2021). "In a murine model of pancreatic cancer, SPARC gene deficiency caused a reduction in expression levels of types I, III, and IV collagen that led to elevated tumor metastases." (PMID 29178186, 2018). "SPARC, for instance, is markedly overexpressed in pancreatic cancer, and its expression is associated with a poorer prognosis." (PMID 29435136, 2018). "Conversely, in breast, melanoma, brain, colon, prostate, kidney, esophageal, lung, and pancreatic cancers, SPARC expression has been associated with a more aggressive phenotype, inhibiting apoptosis and promoting tumor invasiveness and metastases." (PMID 27544129, 2016). "All of these ten studies showed the association between SPARC expression and overall survival of patients with pancreatic cancer." (PMID 26731428, 2016). "In this systematic review with meta-analysis, the elevated SPARC expression, especially in the stroma, was associated with a poor prognosis in patients with pancreatic cancer." (PMID 26731428, 2016). "We collected clinicopathological data from the patients and then analyzed the association of SPARC gene TRR methylation with clinicopathological parameters in patients with pancreatic cancer." (PMID 20338068, 2010). "Our data showed that exposure to risk factors such as tobacco smoke and alcohol use was associated with methylation of CpG Region 2 in the SPARC gene promoter in pancreatic cancer tissues." (PMID 20338068, 2010). "Interestingly, in pancreatic cancer a compartmentalization of SPARC can be observed and stromal SPARC expression is associated with poor patient survival independently of the tumor-derived SPARC." (PMID 33466303, 2021). "Consistently, a role for SPARC has been previously associated to an increase in M2 versus M1 ratio in a murine pancreatic cancer model, suggesting that M1 could also be eliminated in vivo." (PMID 29162623, 2017). "Preliminary results in head and neck and pancreatic cancer have suggested that high SPARC expression could be also associated with response to albumin-bound paclitaxel." (PMID 23638089, 2013). "Our data may indicate that these risk factors cause pancreatic cancer development and progression through induction of SPARC gene methylation." (PMID 20338068, 2010). "Alternatively, malignant SPARC-negative cells such as those found in pancreatic cancer might be susceptible to oncolytic attack if they are surrounded by stromal SPARC-positive cells." (PMID 19337591, 2009). "Additionally, SPARC enhances pancreatic tumour growth in SPARC-null mice, where it is associated with decreased deposition of extracellular matrix and reduced cancer cell apoptosis." (PMID 17876328, 2007). "SPARC was a matricellular protein modulating cell-matrix interactions and was found up-regulated in tumor stroma and associated with poor prognosis in many cancer types, including colorectal cancer, pancreatic cancer, cervical carcinoma, and non-small cell lung cancer." (PMID 33240930, 2020). "Both stromal fibroblast and pancreatic tumor epithelial cells exhibit high levels of SPARC, promoting Paclitaxel delivery inside pancreatic cancer cells." (PMID 39544430, 2024).
pancreatic cancer (continued). "Meanwhile, the methylation status of NPTX2, BMP3 and SPARC genes plays an important role in the prognosis of pancreatic cancer." (PMID 39497722, 2024). "For example, high SPARC expression is positively correlated with poor prognosis in pancreatic cancer, invasive breast cancer, and colon adenocarcinoma." (PMID 39040110, 2024). "Genetic deletion of SPARC in pancreatic tumors results in reduction of collagen deposition and collagen fiber density without affecting PDAC progression, vessel density, tumor incidence, grading or metastatic frequency." (PMID 38744194, 2024). "Clinical investigations on pancreatic cancer focused on the cysteine-rich secreted protein acid SPARC, which confirmed a correlation between Abraxane and SPARC expression." (PMID 37836018, 2023). "Low levels of SPARC expression have been described in ovarian, colorectal and pancreatic cancer, and SPARC promoter methylation has been proposed as an important factor in gastric carcinoma tumorigenesis." (PMID 37481552, 2023). "SOX8 transcriptionally regulated EZH2, which reduced expression of SPARC by promoting the methylation of SPARC, thereby reducing the transport of albumin-bound paclitaxel in pancreatic cancer cells." (PMID 35173526, 2022). "Abnormal methylation of the SPARC gene promoter region that leads to gene expression silencing has been observed in primary pancreatic cancer." (PMID 35211625, 2022). "Some researchers have discovered that SPARC is highly expressed in pancreatic cancer (PC) tissues, and overexpression of SPARC in PC cells can induce epithelial mesenchymal transition (EMT) and stimulate the migration and invasion of cancer cells." (PMID 35042833, 2022). "While SPARC secreted from stromal fibroblasts was suggested to suppress cancer cell proliferation or migration in vitro, SPARC expression in peritumoral fibroblasts correlated with worse prognosis in pancreatic cancer." (PMID 33579227, 2021). "In PDAC, SPARC is secreted by both cancer cells and CAFs but very poorly expressed within pancreatic cancer cells." (PMID 34298680, 2021). "The Authors showed that inhibiting the interaction between SPARC and fibronectin prevents SPARC from inducing tumour growth and induces its pro-apoptotic effect on pancreatic cancer cell, by inducing Caspase-3/7-activity." (PMID 33731188, 2021). "The clearest data about the role of SPARC in tumor angiogenesis are coming from investigations of gastric cancer, bladder cancer, pancreatic carcinoma, and neuro- and glioblastoma." (PMID 34209679, 2021). "It has been demonstrated that SPARC was overexpressed in some cancers, such as pancreatic carcinoma, esophageal squamous cell cancer, and GC." (PMID 34899080, 2021). "Overexpression of SPARC also mediated the suppressing effect of TP53INP1 on the migration of pancreatic cancer cells and promoted the progression of malignant cancers." (PMID 33195283, 2020). "On average, the expression of SPARC in CTCs was higher than in the pancreatic cancer cell lines, PANC1 (p = 0.053) and ASPC-1 (p = 0.004), even though the general distributions of most measured mRNAs were much lower in the CTCs than in the cell-line cells." (PMID 28569190, 2017). "Elevated SPARC protein levels were also demonstrated to promote invasiveness of pancreatic tumour cells." (PMID 28569190, 2017). "SPARC mRNA levels were previously demonstrated to be highly elevated in both chronic pancreatitis (16-fold increase) and pancreatic cancers (31-fold increase), compared to normal pancreatic tissue." (PMID 28569190, 2017). "It was suggested miR-148b and -152 that are modifying methylation status of tumor suppressor genes such as BNIP3 and SPARC can be applied in killing the pancreatic cancer cells and decreasing the tumorigenicity of these cells." (PMID 29262657, 2017). "So, SPARC overexpressed in pancreatic cancer has the potential to improve the invasiveness of cancer cells." (PMID 26731428, 2016).
pancreatic cancer (continued). "And found that the growth of pancreatic tumors in SPARC-null mice were enhanced because of the collagen deposition and fiber formation decreasing." (PMID 26731428, 2016). "Puolakkainen examined the growth of pancreatic tumors in SPARC-null (SP(-/-)) mice and their wild-type (SP(+/+)) counterparts." (PMID 26731428, 2016). "As we all know, this meta-analysis, with a total 10 studies and 1632 patients, was the first systematic review which evaluated the role of SPARC in the prognosis of pancreatic cancer." (PMID 26731428, 2016). "In pancreatic cancer, many studies have investigated the prognostic value of SPARC, in spite of small sample sizes and controversial reports." (PMID 26731428, 2016). "We have further shown that FSTL-1 inhibits pancreatic cancer cell growth, suggesting that SPARC and FSTL-1 produced by stromal cells have antagonistic effects on cancer cell growth." (PMID 27886258, 2016). "And in pancreatic cancer, the results from published reports about the prognostic value of SPARC are also controversial." (PMID 26731428, 2016). "In one study of advanced pancreatic cancer patients receiving gemcitabine and nab-paclitaxel, high stromal SPARC expressers had a statistically significant longer OS than low SPARC expressers on multivariate analysis." (PMID 27544129, 2016). "The pooled HR of OS indicated that high expression of SPARC had a poor survival in patients with pancreatic cancer." (PMID 26731428, 2016). "The pooled hazard ratios (HRs) and corresponding 95%CI of overall survival (OS) were calculated to evaluate the prognostic value of SPARC expression in patients with pancreatic cancer." (PMID 26731428, 2016). "In view of the heated controversy of SPARC, a systematic review of the available articles with meta-analysis is urgent to be performed to evaluate the prognostic value of SPARC in pancreatic cancer." (PMID 26731428, 2016). "This is similar to findings in an earlier phase I/II trial in advanced pancreatic cancer, where only stromal SPARC expression appeared to be an effective marker of increased activity of nab-paclitaxel." (PMID 27411683, 2016). "Supporting a direct role for SPARC in promoting metastasis, murine breast and pancreatic cancer metastasis models have shown that elevated SPARC levels increase metastatic potential." (PMID 26926673, 2016). "In pancreatic cancer, SPARC overexpression was correlated with response rate to nab-paclitaxel and prolonged progression free survival." (PMID 25906748, 2015). "The high levels of SPARC expression evident in virtually all pancreatic CTCs thus raises the possibility that it contributes significantly to the metastatic spread of pancreatic cancer." (PMID 25242334, 2014). "In order to define the functional consequences of SPARC expression in pancreatic cancer cells, we screened a panel of patient-derived, low-passage PDAC cell lines for expression." (PMID 25242334, 2014). "Consistent with the aberrant expression of SPARC in some pancreatic cancer cells, a subset of patient-derived tumor cell lines also coexpress it along with epithelial cytokeratins." (PMID 25242334, 2014). "Secreted protein acidic and rich in cysteine (SPARC) represents another proposed target to facilitate depletion of the tumor stroma in pancreatic cancer." (PMID 24084722, 2013). "In contrast to the role of SPARC in promoting EMT, SPARC expression in ovarian and pancreatic cancer cells decreased tumor growth, increased apoptosis and reduced the ability of cancer cells to induce tumors in nude mice." (PMID 22481923, 2012). "Secreted protein acidic and rich in cysteine (SPARC), also called osteonectin, is a protein located both on pancreas cancer tumor cells and fibroblasts within the peritumoral extracelllular matrix." (PMID 22016635, 2011). "SPARC, a secreted protein involved in cell/matrix interactions, is overexpressed in pancreatic cancer." (PMID 21589862, 2011).
pancreatic cancer (continued). "A previous study showed that the SPARC gene promoter is aberrantly methylated in primary pancreatic cancer tissue." (PMID 20338068, 2010). "Our study also revealed that conditioned medium of pancreatic cancer cells down-regulated endogenous SPARC expression of PSCs." (PMID 19920824, 2010). "In the current study, we determined the methylation status of the SPARC gene promoter in pancreatic cancer cell lines, pancreatic cancer and corresponding adjacent normal pancreatic tissues, chronic pancreatitis tissues, and real normal pancreatic tissues." (PMID 20338068, 2010). "In the current study, we not only confirmed the published data about methylation of the SPARC gene promoter in pancreatic cancer, but we also further revealed the methylation level of the different sites of the CpG island." (PMID 20338068, 2010). "The methylation level of CpG Region 1 was higher in pancreatic cancer tissue than in normal, chronic pancreatitis, and the adjacent normal tissues, but CpG Region 1 of the SPARC gene also was methylated in normal pancreatic tissues." (PMID 20338068, 2010). "Particularly, two papers showed that SPARC wasn't expressed in the majority of primary pancreatic cancer tissues (68%~69%), whereas another study found high expression of SPARC in almost all tumour tissues." (PMID 20338068, 2010). "Another study, however, showed that inhibition of endogenous SPARC enhanced pancreatic cancer cell growth." (PMID 20338068, 2010). "In summary, miRs that specifically target DNMT1 and modulate the methylation patterns of TSGs like BNIP3 and SPARC can potentially be utilised as a therapeutic approach for inducing apoptosis in pancreatic cancer cells and reducing their tumorigenic properties." (PMID 40387409, 2025). "By activating caspase 8, a SPARC N‐terminal peptide may improve the apoptotic cascade and resensitize chemotherapy‐resistant human colon, breast, and pancreatic cancer cells to treatment." (PMID 40415238, 2025). "Cancer‐associated fibroblasts can activate epithelial to mesenchymal transition (EMT) in pancreatic cancer, and the fibroblast GO biological pathway was also characterised by SPARC expression, which promotes tumour cell invasiveness in triple negative breast cancer when released by fibroblasts." (PMID 38426634, 2024). "In addition, fibronectin acts as a molecular switch that determines SPARC function in pancreatic cancer." (PMID 35721704, 2022). "Here, some authors show that secreted protein acid rich in cysteine (SPARC), over-expressed on the surface of different cancer cells including pancreatic cancer might eventually favor Abraxane internalization." (PMID 36362156, 2022). "Moreover, an altered distribution of macrophages was detected in SPARC-/- compared to WT control mice after pancreatic tumor cell injection." (PMID 33466303, 2021). "On the other hand, in pancreatic cancer plasma FN1 acts as a molecular switch, affecting the activity of the matricellular protein, SPARC and controlling whether SPARC promotes pancreatic cancer cell proliferation or induces cancer cell death." (PMID 33731188, 2021). "SPARC may also serves as an unfavorable prognostic marker in pancreatic cancer, as its overexpression may improve cell invasion." (PMID 31296175, 2019). "In types of leukemia like myelogenous leukemia with MLL abnormalities that do not express SPARC, in pancreatic carcinoma, or in ovarian carcinoma, SPARC was associated with tumor suppression." (PMID 31934533, 2019). "In addition, no meta-analyses have formerly been performed on the prognostic significance of SPARC in pancreatic cancer." (PMID 26731428, 2016). "Similar to SPARC, Hevin mRNA is overexpressed in pancreatic cancer compared to normal tissue." (PMID 27886258, 2016). "SPARC is useful for the adjuvant chemotherapy of pancreatic cancer." (PMID 26731428, 2016). "Thus, we carried out a meta-analysis evaluating the relationship between SPARC expression and the prognosis of patients with pancreatic cancer." (PMID 26731428, 2016).
pancreatic cancer (continued). "SPARC is a matricellular protein that is involved in both pancreatic cancer and diabetes." (PMID 27886258, 2016). "SPARC might be an unfavorable indicator in patients with pancreatic cancer, especially in the stroma." (PMID 26731428, 2016). "However, SPARC knockdown by both shRNAs significantly reduced pancreatic cancer cell migration in wound scratch assays and their invasive properties, as measured by in vitro Boyden assays." (PMID 25242334, 2014). "Thus, SPARC expression by pancreatic cancer cells appears to selectively enhance their invasive and migratory properties to augment metastatic virulence." (PMID 25242334, 2014). "Finally, therapy that includes losartan in pancreatic cancer patients that have lost tumor cell expression of SPARC is a potential strategy to control TGFβ-mediated tumor progression." (PMID 22348081, 2012). "In pancreas cancer, it is becoming clear that the location of SPARC overexpression is important." (PMID 22016635, 2011). "The conditioned medium containing secreted SPARC protein suppressed the growth of pancreatic cancer cells, indicating that silencing of the SPARC gene may result in pancreatic cancer development and progression." (PMID 20338068, 2010). "We next performed BSP PCR-based sequencing analysis to assess the methylation status of the SPARC gene TRR in four tissue groups: 40 pancreatic cancer samples and their corresponding adjacent normal pancreatic tissues, 6 chronic pancreatitis samples, and 6 real normal pancreatic tissue samples." (PMID 20338068, 2010). "Methylation of the SPARC gene transcriptional regulation region (TRR) was detected using bisulfite-specific (BSP) PCR-based sequencing analysis in 40 cases of pancreatic cancer and the adjacent normal tissues, 6 chronic pancreatitis tissues, and 6 normal pancreatic tissues." (PMID 20338068, 2010). "Aberrant methylation of the SPARC gene has been reported in various kinds of tumors, including lung and colorectal cancer, acute myeloid leukemia, multiple myeloma, endometrial cancer, ovarian cancer, cervical cancer, pancreatic cancer, and prostate cancer." (PMID 20338068, 2010). "In addition, the in vitro experiment showed that the expression of SPARC inhibited growth of cancer cells, but promoted invasion of pancreatic tumor cells." (PMID 20338068, 2010). "Another reason contributing to the down-regulation of SPARC in human pancreatic cancer cells may be the over-expression of FGFR1-IIIc." (PMID 19920824, 2010). "Detection of SPARC gene methylation may be useful as a tumorigenesis marker for early detection of pancreatic cancer." (PMID 20338068, 2010). "Down-regulation of SPARC in pancreatic cancer cells is believed to depend on DNA methylation." (PMID 19920824, 2010). "Previous studies have shown that SPARC promoter is hypermethylated in pancreatic cancer cells." (PMID 19337591, 2009). "Moreover, SPARC expression by peritumoral fibroblasts portends a poorer prognosis for patients with pancreatic cancer." (PMID 19337591, 2009). "Additionally, SPARC was object of clinical investigations in pancreatic cancer." (PMID 36362156, 2022). "Interestingly, the same group showed that forced expression of MMP-9 rescues the loss of angiogenesis and abrogates metastasis of pancreatic tumors triggered by the absence of host SPARC." (PMID 34298680, 2021). "However, in the estimate, when deleting the study of Mao, we found that a new pooled significant HR = 1.63 (95%CI: 1.25–2.13, P = 0.0003), which supported the negetive prognostic value of SPARC expression in patients with pancreatic cancer, as compared with the old pooled HR with a P = 0.44." (PMID 26731428, 2016). "Finally, recent studies using a mouse model of pancreatic cancer and single-cell RNA sequencing have identified the expression of extracellular matrix genes, including SPARC, in CTC, an interesting finding that the Authors confirmed in CTC from patients with pancreatic cancer." (PMID 25527469, 2014).